CEBPB (CCAAT enhancer binding protein beta)
Diseases named in the same sentence as CEBPB in open-access papers (continued):
Sharing a sentence is not in itself a finding about the gene and the disease.
glioblastoma (46 papers, 2012 to 2026). The most malignant astrocytic tumor (WHO grade IV). "Aberrant CEBPB expression has been implicated in various cancers, including breast, liver, and glioblastoma, suggesting its role in tumorigenesis." (PMID 40949418, 2025). "The transcription factor (TF) CCAAT/enhancer binding protein beta (CEBPB) is associated with the mesenchymal state of primary glioblastoma, and its expression in glioma is important for maintaining the tumor initiating capacity and invasion ability." (PMID 27716259, 2016). "CEBPB was recently identified as a master regulator of a mesenchymal gene expression signature associated with poor prognosis in glioblastoma." (PMID 23046790, 2012). "CEBPB is associated with the development of various tumors, including osteosarcoma, gastric cancer, HCC, glioblastoma, and human acute myeloid leukemia." (PMID 33613623, 2020). "In addition, CEBPB is highly expressed in glioblastoma stem cells and has been shown to promote glioma progression by regulating cyclin D1 and inducing distinct resistance to chemotherapy." (PMID 32084215, 2020). "CEBPB has been studied in the context of cellular transformation and cancer and was recently regarded as one of the master regulators in cancer biology, especially in mesenchymal glioblastoma." (PMID 30847302, 2019). "In connection to previously reported glioblastoma mesenchymal signature transcription factors, SFRP2 increased and correlated with the expression of CEBPB, RUNX1, and FOSL2 in TCGA glioblastomas." (PMID 34021259, 2021). "To test the hypothesis that dn-decoy forms of CEBPB and CEBPD kill cancer cells, we transfected T98G glioblastoma cells with vectors expressing myc-tagged CEBPB or CEBPD leucine zipper sequences, or tag alone." (PMID 34065488, 2021). "This set includes genes with established roles in glioblastoma (for example, PTEN and CEBPB), as well as others not previously implicated in the disease (see Discussion)." (PMID 23046790, 2012). "Moreover, upon JUN, CEBPB and HDAC3 knockdown, the expression levels of MGMT decreased significantly, suggesting that these genes could regulate drug resistance of glioblastoma by mediating MGMT status." (PMID 30775317, 2019). "Regarding previously reported glioblastoma mesenchymal signature transcription factors, SOX2 as opposed to SFRP2, decreased CEBPB and FOSL2 levels consistent with their negative correlation to SOX2 in TCGA glioblastomas." (PMID 34021259, 2021).
glioma (43 papers, 2009 to 2026). A benign or malignant brain and spinal cord tumor that arises from glial cells (astrocytes, oligodendrocytes, ependymal cells). "In a study on glioma, it was shown that CEBPB is associated with the expression of NQO1 and GSTP1 and can regulate the expression of antioxidant enzymes to regulate oxidative stress and mediate tumor growth in the brain." (PMID 38710698, 2024). "In the context of GBM, CEBPB not only governs the proliferation, migration, and invasion of glioma cells 57, but it is also closely linked with the MES subtype of GBM, correlating with unfavorable clinical outcomes." (PMID 38994023, 2024). "Another study showed that the transcription factor CEBPB promoted the development of isocitrate dehydrogenase 1 wildtype (IDH1 wt) gliomas by upregulating P4HA2 protein in glioma cells at the transcriptional level." (PMID 40347062, 2025). "The subsequent in vivo experiment demonstrated that the depletion of CEBPB in transplanted glioma cells visually reduced the growth of the tumors and extended the survival time of the mice bearing glioma cells." (PMID 38994023, 2024). "Consistent with our in vitro results, the depletion of CEBPB in transplanted glioma cells not only significantly reduced the overall TAMs (Iba1 positive) content but also markedly decreased the content of CD206 or CD163 positive M2 TAMs." (PMID 38994023, 2024). "Of these, IRF1, IRF2, and PRDM1 were upregulated in all grades of glioma, while CEBPB was just upregulated in grade III and combined." (PMID 33948562, 2021). "Total 529 DEGs were identified in the normal glioma cells compared with the CEBPB-silenced glioma cells, including 336 up-regulated and 193 down-regulated genes." (PMID 27716259, 2016). "According to the analysis of the microarray dataset, a total of 529 DEGs (including 336 up-regulated genes and 193 down-regulated genes) were identified in the normal glioma cells compared with the CEBPB-silenced glioma cells." (PMID 27716259, 2016). "A total of 529 DEGs were identified in the normal glioma cells compared with the CEBPB-silenced glioma cells." (PMID 27716259, 2016). "Given that DN-ATF5 triggers apoptosis of glioma and other cancer cell types, identification of CEBPB, CEBPD and CCDC6 as direct DN-ATF5 targets suggested that these too may play required roles in tumor cell growth and survival." (PMID 36831248, 2023). "This suggests that among the TFs previously characterized (such as FOSL2, STAT3, BHLHB2, and RUNX1), FOSL1 and CEBPB might play a dominant role in the NF1-mediated MES transition that occurs in a glioma cell-intrinsic manner." (PMID 34399888, 2021). "We conducted a comprehensive bioinformatics analysis to identify genes which may be correlated with CEBPB-silenced glioma." (PMID 27716259, 2016). "Firstly, the differentially expressed genes (DEGs) between SNB19 human glioma cells transduced with non-target control small hairpin RNA (shRNA) lentiviral vectors for 72 h and SNB19 human glioma cells transduced with CEBPB shRNA lentiviral vectors for 72 h were identified and annotated." (PMID 27716259, 2016). "Moreover, consistent with interference with CEBPB, CEPBD and ATF5 activities, in T98G and other non-glioma cancer lines, Dpep and Bpep suppressed expression of direct CEBPB/CEBPD targets IL6 and IL8 and of direct ATF5 and CEBPB target asparagine synthetase (ASNS)." (PMID 36831248, 2023). "Additionally, CEBPB and TCF12 might function in glioma through targeting others (CEBPB → TCF12, CEBPB → TGFBR2, and TCF12 → TGFBR2)." (PMID 27716259, 2016). "However, the regulation mechanism of CEBPB on TGFB1/SMAD3 in glioma was seldom studied." (PMID 27716259, 2016). "CEBPB might act in glioma by regulating CCL2, CCND1, THBS1, THBS2, SMAD5, SMAD6, TGFBR2, and TCF12." (PMID 27716259, 2016). "As we have reviewed thus far, there is abundant evidence to support targeting of ATF5, CEBPB and CEBPD individually for therapeutic treatment of gliomas and an array of other cancer types." (PMID 36831248, 2023).
glioma (continued). "Genes common to the top 5 activated pathways include POSTN, MMP9, CEBPB, CEBPD, and IGFBP5, which reportedly participate in glioma growth, invasion, and immunosuppression." (PMID 35814469, 2022). "We found that 4 of 26 predicted TFs (IRF1, IRF2, CEBPB, and PRDM1) were upregulated at the mRNA level in MR1 high gliomas." (PMID 33948562, 2021). "A microarray expression analysis in mesenchymal gliomas found that expression of BHLHE40 and a number of other transcriptional regulators of mesenchymal transition including CEBPB, CEBPD, and STAT3 correlates with the extent of necrosis." (PMID 27096627, 2016). "C/EBP-β (CEBPB) and STAT3 have previously been shown to synergistically induce mesenchymal transformation of glioma cells." (PMID 23408876, 2013). "Moreover, we observed a strong correlation between CEBPB (C/EBPβ) and RCAN1-4 expression, both at the RNA level in glioma cohorts and at the protein level in the GBM cells we examined." (PMID 41436600, 2026). "Interestingly, we found that most of these ligands (e.g., CSF1, CXCL8, POSTN) 21, 32, 43 are broadly expressed in different glioma subclusters, whereas SPP1 is specifically expressed in the CEBPB+ GBM subcluster." (PMID 38994023, 2024). "To further explore the specific molecular mechanism of this phenomenon, we assessed four transcription factors of Galectin-9 (AR, CEBPA, CEBPB, and TFAP2C) and found that CEBPA on chromosome 19q played a leading role in the transcriptional regulation of Galectin-9 in gliomas." (PMID 34956239, 2021). "Importantly, TGM2 also supports the trans-differentiation of glioma stem cells by triggering degradation of CEBP Homologous Protein (CHOP/GADD153), leading to a reciprocal increase in CEBPβ levels." (PMID 33854178, 2021). "Activated NF-κB can mediate the activation of STAT3, CEBPB, and TAZ by upregulating the expression of CD44, vimentin, and N-cadherin, thereby promoting the invasion, angiogenesis, and therapeutic resistance of glioma." (PMID 34246306, 2021). "The STAT3 pathway may modulate the number of NSCLC- and mesothelioma- ALDHbright cells and, notably, glioma cells of the mesenchymal subtype, which require STAT3 (and CEBPβ) for their survival, exhibited high levels of ALDH1A3 expression." (PMID 25868979, 2015). "This interplay between CEBPB and DDIT3 may be relevant for glioma therapy development, as DDIT3 induction in response to a range of compounds sensitizes glioma cells to apoptosis (see, for example,)." (PMID 23046790, 2012). "Of these, IRF1 (low grade n = 4, high grade n = 4), IRF2 (low grade n = 8, high grade n = 16), and CEBPB (low grade n = 2, high grade n = 7) also showed different and disperse levels of staining in histology (non-detected; +, low; ++, medium; +++, high) from THPA among high- and low-grade gliomas." (PMID 33948562, 2021).
hepatoma (40 papers, 2009 to 2025). "Studies in hepatoma and pheochromocytoma cell lines have shown that the transcription factor encoded by CEBPB (C/EBPβ) promotes expression of DDIT3, another transcriptional regulator that we found to be upregulated in GNS cells." (PMID 23046790, 2012). "Collectively, these results revealed that miR-93-5p inhibited PPARGC1A and CDKN1A genes, thereby decreasing the expressions of transcription factors CEBPB and promoting hepatoma cells proliferation." (PMID 29361788, 2018). "Additionally, in hepatocellular carcinoma (HCC), CEBPB can modulate inflammation-associated oncogenesis by orchestrating cytokine production and promoting an environment conducive to tumor progression." (PMID 41411347, 2025). "In hepatic carcinoma, specifically HCC, CEBPB has been shown to either promote or inhibit hepatic carcinogenesis." (PMID 40226120, 2025). "In hepatocellular carcinoma (HCC), the methylation status of the CCAAT/enhancer-binding protein-β (CEBPB) enhancer directly impacts tumorigenicity." (PMID 36039999, 2022). "Next, we compared binding profiles of CEBPA enhancers between the CEBPA-expressing hepatocellular carcinoma (HCC) cell line HepG2 and non-CEBPA-expressing cell line HeLa by aligning ChIP-seq tracks (ENCODE) of H3K27ac, Pol II, Pol II Ser2, p300, and CEBPB." (PMID 34039742, 2021).
colorectal cancer (39 papers, 2012 to 2026). A primary or metastatic malignant neoplasm that affects the colon or rectum. "In ulcerative colitis–associated colorectal cancer models, CEBPB overexpression has been tied to increased tumor growth via NF-κB/STAT3 pathway activation." (PMID 41411347, 2025). "CEBPB was upregulated and has been implicated in promoting colorectal cancer progression by enhancing inflammatory responses and tumor growth signaling." (PMID 41411347, 2025). "It was found that CEBPB is upregulated in samples of ulcerative colitis-associated colorectal cancer (UCCRC) and constitutes part of an NF-κB-related gene signature." (PMID 40487290, 2025). "In colorectal cancer, upregulation of CEBPB is associated with increased inflammatory signaling, which contributes to tumor growth and metastasis." (PMID 41411347, 2025). "We conducted bulk RNA-seq analysis on colorectal cancer cell lines following CEBPB knockdown to explore its impact on gene expression." (PMID 41411347, 2025). "Elevated expression of CCAAT/enhancer-binding protein beta (CEBPB) accelerates the malignant progression of colorectal cancer (CRC) by activating the PI3K/AKT/mTOR signaling pathway and decreasing CRC cell sensitivity to cuproptosis in a CRC cuproptosis model." (PMID 40406488, 2025). "These insights not only clarify the functional complexity of CEBPB in colorectal cancer but also pave the way for new therapeutic strategies aimed at restoring controlled MAPK signaling." (PMID 41411347, 2025). "Overall, our findings provide fresh insight into how CEBPB shapes the tumor landscape in colorectal cancer and underscore the power of integrated transcriptomic analyses for unmasking pivotal transcription factors and their targets." (PMID 41411347, 2025). "We identified a subset of rescue genes that were dysregulated during colorectal cancer progression and reversed upon CEBPB knockdown, referred to as “rescue genes”." (PMID 41411347, 2025). "Given its broad regulatory role, the upregulation of CEBPB in colorectal cancer suggests its significant involvement in tumorigenesis and progression." (PMID 41411347, 2025). "Based on data from public datasets, the transcription factor CEBPB is more valuable than FOXA1 in evaluating the prognosis of colorectal cancer, so we further explored the regulatory relationship between CEBPB and SERPINA1." (PMID 38710698, 2024). "In the GSE17537 dataset, overall survival was shorter in the high CEBPB expression group of colorectal cancer patients (P = 0.0063)." (PMID 38710698, 2024). "DNA hypermethylation promotes metastasis of colorectal cancer by regulating the binding of CEBPB and TFCP2 to CPEB1 promoters." (PMID 37771430, 2023). "CCL20 secreted by colorectal cancer cells activating FOXO1/CEBPB/NF-κB signaling, promoting the recruitment of Tregs." (PMID 34095111, 2021). "In concordance, the CCL20 secreted by colorectal cancer (CRC) cells can also recruit regulatory T cells (Tregs) to promote chemoresistance via a FOXO1/CEBPB/NF-κB/CCL20 signaling loop in these cells." (PMID 33483477, 2021). "In vivo, 5-FU treatment elevated the expression of CCL20 in colorectal cancer cells (CRC) by activating FOXO1/CEBPB/NF-κB signaling, which promoted the recruitment of Tregs within TME." (PMID 34095111, 2021). "In this study, we found that colorectal cancer cell-derived chemokine (C-C motif) ligand 20 (CCL20) induced recruitment of Tregs via FOXO1/CEBPB/NF-κB signaling, and that Tregs further promoted chemoresistance of CRC." (PMID 31395078, 2019). "Several previous studies in colorectal cancer and other cancers have experimentally manipulated CEBPB expression, and in some cases assessed tumor growth in animal models, consistently reporting that CEBPB exerts pro-tumor effects." (PMID 41411347, 2025). "Within the context of colorectal cancer, accumulating evidence suggests that elevated CEBPB expression may support metastatic traits and worsen patient outcomes." (PMID 41411347, 2025).
colorectal cancer (continued). "The results suggest that SERPINA1 and CEBPB are positively correlated in colorectal cancer." (PMID 38710698, 2024). "Furthermore, CEBPB signaling has been shown to be activated in colorectal cancer cells following treatment with 5-FU, suggesting that CEBPB-mediated activation of DPYD expression might represent a dynamic response to therapy." (PMID 38686795, 2024). "It has been shown that 5-FU therapy increased the expression of chemokine (CCL20) in colorectal carcinoma cells (CRC) in vivo by triggering FOXO1/CEBPB/NF-κB signaling, which aided in the migration of Tregs into TME." (PMID 38347575, 2024). "Here, we used integrated transcriptomic analyses of healthy and colorectal cancer samples from three datasets—TCGA-COAD, GSE100179 and GSE196006, and laboratory assays to uncover CCAAT/enhancer-binding protein beta (CEBPB) as a key driver of CRC." (PMID 41411347, 2025). "In chemo-resistant colorectal cancer, CCL20 recruits Tregs to support the process through the forkhead box protein O1 (FOXO1)/CCAAT/enhancer-binding protein beta (CEBPB)/NF-κB pathway." (PMID 40076892, 2025). "This study has validated the role of CEBPB in UCCRC mice at the animal level; however, the transition from colitis to colorectal cancer is a protracted process that involves epithelial phenotype switching." (PMID 40487290, 2025). "Notably, miR-155, which is often dysregulated in colorectal carcinoma (CRC), inhibits the transcription factor CEBPB, leading to the downregulation of miR-143 and the subsequent upregulation of its target genes, B7-H3 and B7-H4, in cancer cells." (PMID 40214484, 2025). "Here we used a public colorectal cancer dataset to analyze the prognostic significance and clinical relevance of FOXA1 and CEBPB." (PMID 38710698, 2024). "Together, these findings indicate that CEBPB directly targets the DUSP1 promoter and modulates its transcriptional activity, thereby providing mechanistic insight into how CEBPB influences key signaling pathways in colorectal cancer." (PMID 41411347, 2025). "Colorectal cancer (CRC) cells releasing CCL20 attracted Tregs, fostering chemoresistance through FOXO1/CEBPB/NF-κB signaling, which could be a promising strategy for treating CRC." (PMID 39143228, 2025). "Based on the colorectal cancer dataset GSE19860, Spearman’s method was used to analyze the correlation between SERPINA1 and FOXA1 (r = 0.19, P = 0.23) and the correlation between SERPINA1 and CEBPB (r = 0.45, P = 0.0034)." (PMID 38710698, 2024). "Protein factors that could regulate transcription of SMAD4-213 via AnnoLnc2 predicted binding sites upstream of/overlapping TSS that are expressed in colorectal cancer are CDX2, CEBPB, ELF1, NCOA1, NCOR1, NCOR2 and TFAP4." (PMID 39132157, 2024). "To further verify the regulatory relationship between CEBPB and SERPINA1 and their effects on colorectal cancer proliferation, we transfected RKO and Caco2 cells with si-NC and Control, si-CEBPB and Control, and si-CEBPB and SERPINA1, respectively, and performed colony formation assays." (PMID 38710698, 2024). "Furthermore, CEBPB also interacts with FOXO1, NF-kappa B, and CCL20, and FOXO1/CEBPB/NF-kappa B/CCL20 axis has been reported as a target for Colorectal cancer treatment." (PMID 34490085, 2021).
Alzheimer disease (26 papers, 2012 to 2026). A progressive, neurodegenerative disease characterized by loss of function and death of nerve cells in several areas of the brain leading to loss of cognitive function such as memory and language. "We call this CEBPB-driven 33-gene set as mitochondriaobesity/neurodegeneration (Mon)-gene-signature, which at least in Alzheimer’s disease have a connection to γ-Secretase as inhibitors against this enzyme are aimed for Alzheimer’s disease therapy." (PMID 41282072, 2025). "Therapeutically, approaches targeting CEBPB function have been explored in other immune-inflammatory diseases, such as spontaneous hepatitis and Alzheimer’s disease." (PMID 40083558, 2025). "The upregulation of CEBPB in Alzheimer’s disease promotes the expression of proinflammatory genes in microglia and affects macrophage activation." (PMID 41007174, 2025). "CEBPB regulates the expression of genes involved in immune and inflammatory responses to escalate Alzheimer’s disease-related gene expression and pathogenesis." (PMID 39456437, 2024). "CEBPB was up-regulated in patients with Alzheimer’s disease, which increased the expression of pro-inflammatory genes in microglia, and the ubiquitin ligase COP1 inhibited neuroinflammation by silencing CEBPB in microglia." (PMID 35204186, 2022). "In an Alzheimer’s disease model, blocking BDNF/TrkB neurotrophic signaling up-regulated inflammatory factors and activated the JAK2/STAT3 pathway, therefore up-regulating CEBPB." (PMID 35204186, 2022).